CDK12 (cyclin dependent kinase 12)
Diseases named in the same sentence as CDK12 in open-access papers (continued):
Sharing a sentence is not in itself a finding about the gene and the disease.
tumor (continued). "Although tumour SMU087 has both somatic CN loss and deletion detected on CDK12, it did not satisfy the criteria for assessment of CDK12 biallelic loss." (PMID 36045381, 2022). "By using Western blotting to further examine paired adjacent normal colon tissues, primary CRC tumours and liver metastatic CRC tumours, it was shown that CDK12 were boosted in adjacent normal colon tissues, primary CRC tissues and liver metastatic tissues in order." (PMID 36254394, 2022). "Arguably, the opposite anti-proliferative effects of MTX vs. PTX on CDK12-KI/PyMT and WT/PyMT tumor cells did not depend on intrinsic differences in their basal proliferation rate, which appeared to be similar in both cell types." (PMID 35550508, 2022). "Remarkably, the positive correlation between high CDK12 status and favorable prognosis in the treated group was independent of other standard prognostic factors, such as tumor size and number of positive lymph nodes in an adjusted multivariable analysis." (PMID 35550508, 2022). "The results showed that inhibiting the expression of the ICD-related genes CDK12/13 could release HMGB1 and translocate calreticulin, and promote T cell dependent tumor inhibition." (PMID 36437951, 2022). "To further investigate the relationship between CDK12 and PAK2 in tumor growth, we utilized GPS, a kinase-specific phosphorylation prediction tool, to find that CDK12 may phosphorylate PAK2." (PMID 32483448, 2020). "Studies have indicated that THZ1, a CDK12 inhibitor, inhibits MYC expression and tumor growth." (PMID 32570740, 2020). "A future challenge for drug development will be to design small molecules that target cell-cycle CDKs and transcriptional CDKs without inhibiting CDK10 and other CDKs that can act as tumor suppressors, such as CDK12." (PMID 32175313, 2020). "There were no significant tumor volume or weight reductions in the CDK12-intact lines." (PMID 39071291, 2025). "Thirdly, although the samples were derived from tumor-enriched regions from biopsies, we could not establish a limit for the contribution of the CDK12-mut tumor cells and TME to the MHC expression since the RNA-seq relies on data from bulk tissue." (PMID 38704603, 2024). "No mutations in CDK12 and CDK13 genes were detected in these HGSOC tumor specimens or PDOs." (PMID 37202753, 2023). "We next obtained the cell lysates from the xenografted tumours, and to perform Western blotting analysis, the data showed that SR‐4835 administration resulted in a remarkable decrease in phosphorylation of RNA Pol II CTD at S2 instead of S5, indicative of the in vivo anti‐CDK12 power of SR‐4835." (PMID 36254394, 2022). "For the two cases of mutation with loss of heterozygosity, although there was no decrease in CDK12 copy numbers in both of them, we judged them to be biallelic loss because only the pathogenic allele was present as the VAF was almost equal to the tumor content." (PMID 36271301, 2022). "No of mice tumor/no of transplanted mice with A2780 and CDK12 KO A2780 cells." (PMID 35912188, 2022). "Among the rationale combination therapies evaluated, THZ531, a CDK12 inhibitor, was found to synergize with PARP inhibitors to prevent DNA damage repair and induce tumor cell death in EwS, significantly diminishing the tumor growth in mouse xenograft and PDX models of the disease." (PMID 32344731, 2020).
tumor (continued). "Indeed, targeting CDK12 activity itself or the glycolytic/SGOC metabolism using molecular genetics or pharmacological approaches led to profound attenuation, or even complete reversion, of CDK12-dependent tumor phenotypes in vitro, and severely curbed tumorigenicity and metastatic spreading in vivo." (PMID 35550508, 2022). "Elevated CDK12 expression was independent of TNM stage but was enriched in aggressive subtypes, suggesting its potential role in tumor progression." (PMID 41491919, 2026). "After tumor establishment, mice were assigned to 4 groups: (a) non-targeting plus vehicle, (b) non-targeting plus TMZ, (c) CDK12 shRNA plus vehicle, and (d) CDK12 shRNA plus TMZ." (PMID 40996961, 2025). "We successfully grew tumor chunks from new PDX line LTL706B in mouse renal capsules and then confirmed immunopositivity for PCa markers (AR, KRT8, and PSMA) and absence of CDK12." (PMID 39368479, 2024). "All the cases showed a significant suppression of tumor growth by procaterol, especially in the CDK12 high expression level case LSG39, LSG38, LSG45 compared to the relatively low level of CDK12 LSG36, without demonstrating significant toxicity." (PMID 32483448, 2020). "Finally, we leverage paralog-based synthetic lethality to demonstrate that murine and human tumor tissue lacking functional CDK12 is sensitive to CDK13 inhibition and degradation—a finding with future clinical applicability in CDK12-mutant cancers." (PMID 39368479, 2024).
cancer (160 papers, 2012 to 2026). A tumor composed of atypical neoplastic, often pleomorphic cells that invade other tissues. "Such diversity in alteration type underlies the dual functional spectrum of CDK12/13 across human cancers, discussed in the following sections." (PMID 41491919, 2026). "CDK12-deficient tumors exhibit strong cytokine induction and T-cell infiltration, consistent with the immunogenic phenotype observed in other CDK12-mutant cancers." (PMID 41491919, 2026). "Aberrant CDK12 expression or mutation is implicated in cancer initiation, progression, and treatment response." (PMID 40166687, 2025). "The top candidate CHIP mutations included a missense mutation (p.R708L) in CDK12, which encodes cyclin-dependent kinase 12, a protein involved in the tumorigenesis of several cancers." (PMID 40365343, 2025). "Here, we provide the first evidence to our knowledge that CDK12 inactivation activates the cGAS/STING pathway, which in turn drives T cell recruitment in CDK12-deficient cancers." (PMID 40955658, 2025). "Inhibition or loss of cyclin-dependent kinase 12 (CDK12) triggers a transcriptional elongation defect that results in deficiencies in DNA damage repair, producing genomic instability in a variety of cancers." (PMID 38481813, 2024). "A recent study analyzing a broad range of cancer types demonstrated that CDK12 alterations are associated with the tandem-duplicator phenotype in cancer." (PMID 39706915, 2024). "CDK12 mutations are found in many types of cancer, but the exact function of CDK12 in the initiation and progression of cancer is not fully understood." (PMID 38736108, 2024). "In general, for both pPCa and mCRPC cancers, CDK12 -mut tumors expressing higher MHC levels were associated with transcriptomic changes that indicate a general pattern of activation of IFN-γ-responsive and cytotoxic activity genes." (PMID 38704603, 2024). "Amazingly, CDK12‐mutated cancer cell lines are most sensitive to dihydro‐rotenone, a known inhibitor of mitochondrial ETC complex I and the only one among nearly 300 tested compounds that shows significance." (PMID 38736108, 2024). "CDK12 is involved in cancer dysregulation via both gain of function with gene amplification and loss of function with mutations encoding the CDK12 locus." (PMID 37342192, 2023). "This feature makes DNA damage-response genes especially susceptible to the inhibition of CDK12, providing a possible point of weakness in CDK12 and, thus, a new opportunity for cancer therapies." (PMID 37626854, 2023). "CDK12/13 inhibition impairs expression of several cancer-relevant genes by causing premature termination of their transcripts and reduction of the corresponding proteins." (PMID 37202753, 2023). "In other cancers, including ovarian, prostate, and breast, loss of CDK12 leads to the downregulation of DDR genes, which increases genomic instability and sensitivity to chemotherapy." (PMID 38104154, 2023). "In summary, stimulation of Pol II pause release at the signal-responsive genes underlies the functional dependence of CDK12-inhibited cancer cells on P-TEFb." (PMID 37811895, 2023). "Dysfunction of CDK12 is associated with the progression and metastasis of a subset of cancers, which affects response to antineoplastic agents." (PMID 37205756, 2023). "A recent study showed that loss of CDK12 in cancer cells results in premature cleavage and polyadenylation of DDR gene transcripts, leading to decreased DNA damage response and lower recovery of affected cells." (PMID 37190191, 2023). "In this analysis of 4994 patients with cancer having undergone clinical‐grade genomic sequencing, 39 (0.78%) were identified to have pathogenic CDK12 alterations." (PMID 34898046, 2022). "This analysis also demonstrated differences between tCDK paralogs regarding their association with the prognosis of different types of cancer, as illustrated by opposite associations between CDK12 and CDK13 expression and KIRP prognosis." (PMID 36577800, 2022).
cancer (continued). "Several studies have shown that CDK12 mutation or deficiency causes cancer cells to be more sensitive to PARP inhibitors." (PMID 35873570, 2022). "As a transcription-associated CDKs, the dysregulation of the CDK12 gene has been recently reported in different types of malignancies and contributes to cancer progression and aggressiveness." (PMID 33628849, 2021). "CDK12 plays a key role in many cellular processes and is mutated or overexpressed in various types of cancer." (PMID 34686673, 2021). "CDK12 mutations are associated with a genomic pattern of tandem duplications in multiple cancer types, including mPC." (PMID 34877933, 2021). "Accordant with its function in the maintenance of genomic stability and cell-cycle regulation, the loss or overexpression of CDK12 is associated with the progression and metastasis of cancers." (PMID 33628849, 2021). "CDK12 is unique among transcription-associated CDKs in that it is subject to somatic genetic alterations in cancer." (PMID 32397434, 2020). "Loss-of-function (LOF) mutations of CDK12 contribute to genomic instability, underlying the genesis of the cancer by causing defects in multiple DNA repair signaling pathways." (PMID 32570740, 2020). "While there is not a great abundance of trials directlyusing CDK12 inhibitors, other potential SL partners are being modulatedin CDK12 deficient cancers, thus giving an SL effect." (PMID 33135887, 2020). "Numerous evidences proved that CDK12 mutation or deficiency lead to cancer cells sensitivity to PARPi." (PMID 32563252, 2020). "Disruption of CDK12 underlies the tandem duplicator phenotype that is enriched in several cancers including triple-negative breast cancer, ovarian, prostate, endometrial, and liver cancers." (PMID 31259151, 2019). "Nevertheless, our analysis suggests that there are at least nine cancer types with a CDK12 mutation prevalence between 1-4%, hopefully prompting further exploration of immunotherapy approaches using a basket-trial design." (PMID 31360735, 2019). "We propose that DNA replication and HR DNA repair defects as a consequence of CDK12 inactivation underlie the genome instability phenotype observed in many cancers." (PMID 31347271, 2019). "Currently, there is only one other report describing cancer patient carrying the CDK12 c.1047-2A>G nucleotide variant." (PMID 30333958, 2018). "Impaired DDR and accumulation of DNA damage is a typical hallmark of cancer, which directly links CDK12 deficiency to tumorigenesis." (PMID 29090014, 2017). "Taking into account that CDK12 plays a critical role in multiple cellular processes and is mutated or overexpressed in various types of cancer, CDK12 inhibition emerges as a favorable strategy for cancer treatment." (PMID 29090014, 2017). "We suggest that cancer-causing mutations in CDK12 debilitate the human CAR system and that this contributes to genome instability and cancer." (PMID 23613755, 2013). "Interestingly, very few cancer cell lines harbor CDK12/13 mutations or deletions, which points to a possible reduced fitness of such clones when cultured in vitro." (PMID 41491919, 2026). "In mammals, CDK12 is reported to be related to the cell's response to DNA damage, and its dysregulation is associated with various types of cancer, making it a potential therapeutic target for cancer treatment." (PMID 40318064, 2025). "Furthermore, CDK12 loss–related genomic patterns have been detected with other genomic signature frameworks, emphasizing the importance of CDK12 in cancer progression." (PMID 40736012, 2025).
cancer (continued). "In summary, our study systematically analysed the diagnostic, prognostic, and immunological relevance of CDK12 across cancers, and it may serve as an ideal biological marker for early cancer diagnosis and the prediction of patient prognosis." (PMID 38503865, 2024). "Additionally, we used immune infiltration analysis to explore the immunological mechanisms underlying the impact of CDK12 on cancer development." (PMID 38503865, 2024). "Moreover, high expression levels of CDK12 were significantly associated with cancer cell invasion and metastasis, as well as poor prognosis in multiple types of cancer." (PMID 38503865, 2024). "Additionally, mutational studies have shown that amplification and missense mutations are the predominant mutational events affecting CDK12 across cancers." (PMID 38503865, 2024). "In patient GP5, CDK12 inactivation was among the first mutations, leading to a PrCa tandem duplicator phenotype and initiating the cancer around age 50, followed by rapid cancer evolution after age 57, and metastasis around age 59, 5 years prior to prostatectomy." (PMID 37828555, 2023). "Following large‐scale cancer sequence analysis, mutations in other HR‐related genes such as CDK12, ATM and PALB2 were commonly found in mCRPC, and these non‐BRCA DNA repair genes could be used as alternative biomarkers to predict the sensitivity of PARPi." (PMID 36694344, 2023). "It has been hypothesized that PARP inhibitors could be effective in CDK12‐deficient cancers, as CDK12 mediates DNA repair via homologous recombination." (PMID 34898046, 2022). "While hypothesis generating in nature and not accounting for confounding factors, we observe a potential signal of longer OS in patients with CDK12‐mutated cancers having received an immune checkpoint inhibitor‐containing regimen." (PMID 34898046, 2022). "In addition, clinical trials evaluating immunotherapy response in CDK12‐mutated cancers are underway." (PMID 34898046, 2022). "While both CDK12 gain- and loss-of-functions were observed in cancer, the mechanisms involved in CDK12 regulation remain unknown." (PMID 36309522, 2022). "CDK12 has been implicated in cancer pathology, such as cell invasion, suggesting that aberrant CDK12 expression may have oncogenic properties." (PMID 33805800, 2021). "The presence of FTDs in CDK12-mutated cancers may result in highly recurrent gains of genes involved in cell cycle and DNA replication." (PMID 32570740, 2020). "These CDK12 mutations were sporadic, but most of these mutations were either nonsense, indel, or missense mutations in the protein kinase domain, suggesting potential loss of CDK12 function in this type of cancer." (PMID 32451425, 2020). "Combination therapy comprising a PD-1 inhibitor and a PARP inhibitor may be an effective approach in patients with CDK12-deficient cancers." (PMID 31259151, 2019). "It is thus important to clarify the prevalence of germline CDK12 variants that may represent constitutive cancer susceptibility alleles." (PMID 31259151, 2019). "Consequently, CDK12 loss leads to increased genomic instability, which is a typical feature of these tumors and represents one of the hallmarks of cancer progression." (PMID 29090014, 2017). "However, an HRd phenotype resulting from CDK12 loss has not been confirmed in assessments of patient tumors or clinically with therapeutics that exploit HRd, and there are conflicting reports on the presence of HRd-associated genomic ‘scars’ in CDK12 mutant cancers." (PMID 39071291, 2025). "Moreover, the ROC curves indicated that CDK12 showed diagnostic value in eight cancer types." (PMID 38503865, 2024).